IL13RA2 (interleukin 13 receptor subunit alpha 2)
Diseases named in the same sentence as IL13RA2 in open-access papers (continued):
Sharing a sentence is not in itself a finding about the gene and the disease.
glioma (continued). "In conclusion, this study demonstrates the feasibility of locoregional IL-13Rα2-targeted CAR-T cell therapy in high-grade glioma, offering significant translational insights crucial for advancing CAR-T cell therapies in glioma treatment." (PMID 38592708, 2024). "Locally delivered IL-13Rα2 and HER2 CAR-T cells demonstrated favorable tolerability and positive clinical outcomes in glioma treatment." (PMID 39506843, 2024). "For instance, in a preclinical study targeting IL13Rα2-positive gliomas, the expression of IL-15 significantly extended the survival of IL13Rα2-CAR T cells and improved their efficacy against gliomas." (PMID 39506843, 2024). "We evaluated the relationship between the expression levels of IL-13Rα2 and FUS and clinicopathological parameters among glioma patients." (PMID 37158824, 2023). "In the present study, the expression of IL-13Rα2 and FUS was measured in a glioma tissue array by immunohistochemistry." (PMID 37158824, 2023). "Pearson’s correlation analysis revealed a positive correlation between IL-13Rα2 and cytoplasmic FUS expression (p = 0.0129; r = 0.3565) in glioma." (PMID 37158824, 2023). "T cells expressing IL13Rα2-CAR with a short spacer region and the internal domains CD28.ζ, 41BB.ζ, and CD28.OX40.ζ demonstrated significant anti-glioma activity in vivo." (PMID 37304305, 2023). "In the context of gliomas, this APC nanoparticle was used to expand human HA-1–specific CD8+ T cells and to generate IL-13Rα2–specific CD8+ T cells to target glioma cells." (PMID 36719372, 2023). "This mAb bound IL-13Rα2 in GBM tissue and improved survival of mice with orthotopic human glioma xenografts." (PMID 35464460, 2022). "Importantly, mice that underwent complete IL-13Rα2-positive tumor regression were also protected against rechallenge with IL-13Rα2-negative tumors, suggesting that the IL-13Rα2-specific CARs assist in the development of diversified long-term anti-glioma immunity." (PMID 35464460, 2022). "The clinical trials, ClinicalTrials.gov NCT identifiers: NCT02208362, NCT01454596, NCT01109095, targeting IL-13Rα2, EGFRvIII, and HER2, respectively, provide useful insights on the immunotherapeutic ability of CAR T cells against gliomas." (PMID 34084145, 2021). "Pep-1, as a specific ligand of interleukin 13 receptor α2 (IL-13Rα2) with high specificity and affinity, can interact with IL-13Rα2, thereby passing the blood–tumor barrier (BTB) and homing in on the glioma." (PMID 34683908, 2021). "Although there was an early promise for IL-13Rα2-directed CAR T-cell therapy, previous studies highlighted the limited persistence of these T-cells resulting in the recurrence of antigen-positive gliomas." (PMID 34572775, 2021). "This approach has yielded fruitful results in preclinical glioma models, as shown by the development of tandem CAR T cells that bind HER2 and IL13Rα2, as well as trivalent CAR T cells targeting HER2, IL13Rα2 and EphA2." (PMID 34298615, 2021). "Notably, the EGFR and IL13Ra2 glioma markers were clearly detected after neuronal conversion at 20 days after Neurog2 infection 42–44, suggesting that the newly converted neurons may still have retained characteristics of GBM cells, at least for the early time period after conversion." (PMID 33755378, 2021). "Transgenic expression of cytokines, such as IL-15, was also demonstrated as a mean to improve anti-glioma activity of CAR-T cells, as shown with IL13Rα2-CAR-T cells." (PMID 33154756, 2020). "IL13Rα2-specific CAR T cells targeted and killed high-grade glioma cells and glioma stem-like initiating cells in vitro, as well as caused the regression of established human glioblastoma orthotopic xenografts." (PMID 31847387, 2019). "We have shown that IL13Rα2-CAR T cells have potent antitumor activity in preclinical GBM models, and that expression of secretory (s) IL15 further enhances their anti-glioma activity." (PMID 30400835, 2018).
glioma (continued). "Expression of sIL15 or mbIL15 significantly enhanced the expansion of IL13Rα2-CAR T cells upon stimulation with U373 glioma cells and CAR T cells expressing sIL15 secreted significantly higher amounts of INFg when compared to IL13Rα2- CAR.mbIL15." (PMID 30400835, 2018). "The expression of IL-13Rα2 and EGFR in glioma cell lines used in our studies was first determined (respectively)." (PMID 29203859, 2017). "Similar findings were observed in another human glioma cell line U251MG, which has a high endogenous expression of IL-13Rα2." (PMID 29203859, 2017). "Next, we validated the specificity of Ad5FFscFv47-CMV-GFP in vivo using intracranially implanted IL13Rα2+ U251MG and IL13Rα2.KDU251MG cells in a xenograft murine model of glioma." (PMID 26656559, 2015). "Querying multiple gene expression databases, we show that IL13Rα2 expression increases with glioma malignancy grade, and expression for high-grade tumors is bimodal, with approximately 58% of WHO grade IV gliomas over-expressing this receptor." (PMID 24204956, 2013). "A fusion protein consisting of interleukin 13 (IL-13) and a mutated form of Pseudomonas exotoxin (IL-13-PE) has also been shown to induce potent and specific cytotoxicity in glioma cells that overexpresses the receptor for IL-13, IL13 receptor-α2 (IL13-Rα2)." (PMID 20942909, 2010). "Locoregional IL-13Rα2-targeted CAR T cell therapy, including intratumoral and intraventricular injections, has shown promise for high-grade gliomas, suggesting that locoregional delivery may mitigate the need for lymphodepletion." (PMID 39199630, 2024). "Treatment with ICG-001 (0–10 μM) showed a concentration-dependent cytostatic effect in all tested human patient-derived glioma cell lines (PBT017, PBT030, PBT135, PBT144, and PBT147) and all murine-derived glioma cell lines (K-luc, GL261-parental, and GL261.IL13Rα2 engineered)." (PMID 38449858, 2024). "For example, dual-target CAR-T cells (e.g., targeting EGFR and IL-13Rα2, targeting EGFRvIII and wide-type EGFR protein) and triple-target CAR-T cells (e.g., targeting EphA2, IL-13Rα2, and EGFRvIII) have demonstrated promising potential in glioma therapy." (PMID 39506843, 2024). "CAR‐T cells were exposed to three different concentrations of recombinant IL‐13Rα2Fc chimeric protein or conditioned medium obtained from IL‐13Rα2 positive (U251) and IL‐13Rα2 negative (T98G) human glioma cell lines." (PMID 38685487, 2024). "In the present study, we also observed that IL-13Rα2 negative glioma cells are not killed by either labeled or unlabeled CAR-T cells." (PMID 37286997, 2023). "It is well known that IL-13Rα2 is overexpressed by high-grade gliomas (HGG), but not expressed at significant levels by low-grade gliomas (LGG) or normal brain tissue." (PMID 37158824, 2023). "In contrast, no cell killing was observed with IL-13Rα2 negative T98G glioma cells with non-labeled and radiolabeled CAR-T cells." (PMID 37286997, 2023). "In the present study, we have used 89Zr-oxine to radiolabel the IL-13Rα2 specific CAR-T cells and tested their biological quality attributes in three naturally occurring IL-13Rα2 positive and one IL-13Rα2 negative glioma cell lines." (PMID 37286997, 2023). "Co-culture of IL-13Rα2 positive and IL-13Rα2 negative glioma cells with varying number of unlabeled and radiolabeled CAR-T cells showed similar cytotoxic activity and released similar amount of IFN-γ." (PMID 37286997, 2023). "Further, encouraging results were published in an adult patient treated this time with autologous IL13Rα2 CAR T as part of a clinical trial investigating the efficacy of IL13Rα2 CAR T cells, open to patients over the age of 12 with recurrent or refractory glioma (NCT02208362)." (PMID 36505819, 2022). "Moreover, IL-13Rα2 activates src, phosphatidylinositol 3 kinase (PI3K), Akt, and mTOR in glioma cells." (PMID 34201539, 2021).
glioma (continued). "These IL13-zetakine CAR T cells were specifically and potently activated in the presence of IL13Rα2-expressing glioma cells, whereas no appreciable effect was seen in the absence of IL13Rα2 expression." (PMID 34298615, 2021). "We have demonstrated up-regulation of two AP-1 transcription factors (c-Jun and Fra-1) at mRNA and protein levels upon treatment with IL-13 in IL-13Rα2 positive but not in IL-13Rα2 negative glioma cell lines." (PMID 30572904, 2018). "Neither mRNA nor proteins of the AP-1 transcription factors were upregulated after IL-13 treatment of IL-13Rα2 negative T98G glioma cell line." (PMID 30572904, 2018). "In the present study, we demonstrate that IL-13/IL-13Rα2 axis is important in mediating signal transduction by upregulating the AP-1 transcription factors in IL-13Rα2 positive, but not in IL-13Rα2 negative glioma cell lines." (PMID 30572904, 2018). "Furthermore, viruses have been designed to specifically target receptors that are overexpressed in glioma cells including PDGFR, IL-13RA2, and EGFRvIII." (PMID 30366424, 2018). "T98G glioma cells were considered IL-13Rα2 negative as these cells expressed extremely low levels of IL-13Rα2 mRNA, but no detectable surface expression by immunostaining." (PMID 30572904, 2018). "Thus, the aim of this study was to generate IL13Rα2-CAR.sIL15 and IL13Rα2-CAR.mbIL15 T cells, and compare their anti-glioma activity." (PMID 30400835, 2018). "Knockdown of IL-13Rα2 expression significantly reduced glioma migration in U87MG, but did not affect cell proliferation." (PMID 29203859, 2017). "IL13Rα2+ U251MG cells retained a very high (above 92% positive cells) expression of IL13Rα2 on their cell surface after lentiviral transduction, whereas IL13Rα2.KDU251MG glioma cells were mostly IL13Rα2 negative (about 12% of IL13Rα2-positive cells)." (PMID 26656559, 2015). "IL13Rα2 is expressed by a high percentage of gliomas, but not at significant levels on normal brain tissue, and in IL13Rα2-expressing tumors has been identified on both stem-like malignant cells and their more differentiated counterparts." (PMID 24787244, 2014). "In reconciling these observations, we determined that the putative IL13Rα2-specific antibody B-D13 recognizes VCAM-1, and that cytokine induction is not a viable approach to increase cell surface expression of IL13Rα2 for therapeutic targeting of gliomas." (PMID 24787244, 2014). "First, the U251T glioma cell line does not express the B-D13-PE recognized antigen, even though this glioma cell line is known to express high levels of IL13Rα2." (PMID 24787244, 2014). "We do not, however, find any evidence for induction of IL13Rα2 through TNF/IL-4 or TNF/IL-13 cytokine regimens on glioma cell lines, either established (T98 or U251T) and/or low-passage primary lines (PBT003-4, PBT008, PBT017-4)." (PMID 24787244, 2014). "While this work calls into question previous studies that have used the B-D13 antibody to assess IL13Rα2 expression, it also suggests that TNF may have significant effects on glioma biology by up-regulating VCAM-1." (PMID 24787244, 2014). "Additionally, within high-grade gliomas (WHO III and IV), IL13Rα2 expression also increases with malignancy grade, with a 2.5-fold increase for WHO grade IV versus grade III tumors (p=2.9 x 10-8)." (PMID 24204956, 2013). "Glioma IL13Rα2 expression did not display consistent correlation patterns with genes defining the neural and classical subclasses of Verhaak." (PMID 24204956, 2013). "IL13Rα2 is one such antigen, expressed by a high percentage of gliomas but not at significant levels on normal brain tissue." (PMID 24204956, 2013). "High grade gliomas frequently overexpress an IL13 receptor subtype, designated IL13Rα2." (PMID 23426187, 2013). "The IL-13Rα2 antigen is a promising target for immunotherapy because it is highly expressed on glioma cells but not on host CNS cells." (PMID 22190972, 2011).
glioma (continued). "Intracavitary (resection-cavity) infusions of first-generation IL13(E13Y)-zetakine CAR T cells were well tolerated in 3 patients, producing transient anti-glioma activity in 2/3, with reduced IL-13Rα2 expression and new tumor necrosis on MRI (no grade ≥3 toxicity)." (PMID 41218126, 2025). "These CAR‐T cells regressed IL‐13Rα2+ve glioma xenografts in vivo without any general toxicity." (PMID 38685487, 2024). "An Immunohistochemistry study demonstrated that in high-grade (WHO grade III–IV) glioma samples, there was a clustering of antigen expression into “distinct neighborhoods.”53 For example, in areas of pseudopalisading necrosis, IL-13Rα2 and HER2 were expressed, but EGFR was not." (PMID 38486856, 2024). "Similarly, CAR‐T cells invaded and migrated to the conditioned medium from IL‐13Rα2 positive U251 and U87 glioma cells but not to the conditioned medium from IL‐13Rα2 negative T98G glioma cells." (PMID 38685487, 2024). "Next, we examined the effect of 89Zr-oxine radiolabeling on cell migration of CAR-T cells using a Boyden chamber assay to measure the response to IL-13Rα2Fc chimeric protein or conditioned medium obtained from IL-13Rα2 positive and IL-13Rα2 negative human glioma cell lines." (PMID 37286997, 2023). "Similarly, unlabeled and radiolabeled CAR-T cells migrated equally and migrated to conditioned medium from IL-13Rα2 positive glioma cells but not to condition medium from IL-13Rα2 negative glioma cells." (PMID 37286997, 2023). "However, the expression of IL-13Rα2 and FUS, their relationship with clinicopathological parameters and their prognostic value in glioma remain unclear." (PMID 37158824, 2023). "Despite these studies, it is not known whether IL-13 can signal through IL-13Rα2 in human glioma tumors in situ and whether it utilizes AP-1 pathway." (PMID 30572904, 2018). "For further validation of IL-13Rα2-dependent infectivity of Ad5FFscFv47-CMV-GFP, we performed an analysis of viral transduction in U87MG and U25MG cell lines, as well in patient-derived primary GBM43 and GBM39 glioma cells, which endogenously express IL13Rα2 at different levels." (PMID 26656559, 2015). "Instead we demonstrate by immunoprecipitation experiments and mass spectrometry that the antigen recognized by the B-D13 antibody following cytokine stimulation is VCAM-1, and that VCAM-1, but not IL13Rα2, is induced on glioma cells by TNF alone or in combination with IL-13 or IL-4." (PMID 24787244, 2014). "By flow cytometry, the IL13Rα2-positive glioma cell lines (PBT015, PBT017-4, PBT030, PBT036, U251T) generally express higher levels of the mesenchymal adhesion markers CD44 and CD54/ICAM-1 than the IL13Rα2-negative glioma lines (PBT003-4, PBT008, PBT009, PBT022)." (PMID 24204956, 2013). "However, in HGG, co-expression of IL-13Rα2 and nuclear and cytoplasmic FUS was correlated with worse OS, which suggested that the combination of these two markers might be a more precise approach to predict glioma progression." (PMID 37158824, 2023). "Although these studies were not undertaken in models of glioma, their approaches are highly applicable as checkpoint-inhibitor-mediated PD-1 blockade previously has been shown to significantly enhance the effector functions of IL-13Rα2 CAR T cells in animal glioma models." (PMID 30863720, 2019). "Taken together, these results indicated that IL-13Rα2 could be exploited as a prospective receptor and PEG-PLGA nanoparticle modified with the high affinity and specificity ligand Pep-1 was a potential targeting drug delivery system for glioma treatment via improving the penetration across BTB." (PMID 26567528, 2015). "We next determined the potency of CAR‐T cells by IFN‐γ release assay when CAR‐T effector cells were co‐cultured with two different IL‐13Rα2 positive target glioma tumour cell lines (U251 and U87MG) and one IL‐13Rα2 negative glioma cell line (T98G)." (PMID 38685487, 2024).
glioma (continued). "Targeted IL-13Rα2 knockdown showed only modestly reduced or no detectable change in STAT3 in wtEGFR-expressing cell line and primary glioma cultures derived from GBM patient tumors, respectively." (PMID 29203859, 2017). "However, not every glioma specific TAPP was found to be elevated in these SCLC samples, e.g., IL-13Rα2." (PMID 26175925, 2015). "Moreover, the IL13Rα2-positive lines frequently display lower CD133 expression than do the IL13Rα2-negative lines, consistent with previous reports that high CD133 expression by glioma cell lines grown in neural stem cell media is indicative of a proneural phenotype." (PMID 24204956, 2013).